MAPK3 (mitogen-activated protein kinase 3)
Diseases named in the same sentence as MAPK3 in open-access papers (continued):
Sharing a sentence is not in itself a finding about the gene and the disease.
cancer (continued). "It is worth pointing out that since proteins within Gene EGFR and Gene HRAS affect multiple cancers as compared to proteins within Gene MAPK3 which are unique to each type of cancer, the cost benefit payoff ratio would be higher for Gene EGFR and Gene HRAS than for Gene MAPK3." (PMID 34764329, 2021). "We also noticed that cases with high-grade malignancy varied significantly in gene expression of Sha-miR-71a and MAPK-3 compared to those with low-grade malignancy and expression levels were increased in high grade cancer (RQ value was significantly different from low grade cancer cases)." (PMID 33139749, 2020). "Targeted therapies can come in many forms, from antibody treatments, such as Herceptin, or treatment involving inhibitors to important enzymes, including upregulated kinases, such as mitogen-activated protein kinase 3 (MAPK3), which has abnormal expression in many forms of cancer." (PMID 33187160, 2020). "Researchers have suggested the impact of metformin on MAPK3 for cancer patients." (PMID 30949321, 2019). "For example, MAPK3, transforming protein p21 (HRAS), and v-akt murine thymoma viral oncogene homolog 1 (AKT1) were all reported as highly related to the MAPK signaling pathway (KEGG ID: map 04010) known to be associated broadly with many cancers." (PMID 30255812, 2018). "Deciphering which of these partners, such as FOXP1, CtBP1, MAPK3, GATAD2B, might be involved in oncogenic process along with FOXP2 should improve our understanding of gene networks underlying cancer progression." (PMID 29725501, 2018). "Expression of MAPK3 is dysregulated in several cancers including breast." (PMID 27942580, 2016). "RPKS6KA3 is part of the MAPK3 pathway, and promotes proliferation in multiple cancer types." (PMID 25992613, 2015). "In addition, drugs targeting the MAPK3/1 pathway are intensively being developed and tested in clinical trials for various human cancers." (PMID 20808308, 2010). "This possible interaction between the AMPK and MAPK3/1 pathways may have considerable implications because both pathways are potential targets for cancer treatment and prevention." (PMID 20808308, 2010). "It remains controversial how MAPK3/1 activation affects behaviour of different cancers." (PMID 20808308, 2010). "In this regard, examining AMPK and MAPK3/1 status in cancer tissue may be important in future clinical trials." (PMID 20808308, 2010). "It was preliminarily predicted that NR could regulate the targets of CASP3, AKT1,ESR1,ACTB,MAPK3 and may modulate various pathways like estrogen signaling, thyroid hormone signaling pathway, prolactin signaling pathway, proteoglycan in cancer pathway, endocrine resistance pathway." (PMID 36401485, 2022). "The high degree of interaction observed in genes like MAPK3, MAP3K1, SRC, and RAF1 further supports their roles in regulating cellular signaling, which is crucial for understanding cancer biology and therapeutic resistance." (PMID 40136517, 2025). "These proteins are involved in critical cancer-related pathways, including SRC in the MAPK signaling pathway, ABL1 in JAK/STAT signaling, PIK3CA in the PIK3-Akt pathway, and MAPK3 in the Ras signaling pathway." (PMID 40105884, 2025). "In contrast, seven out of ten anti-AD core targets (PTGS2, MAPK1, MAPK3, JUN, ESR1, IL6, and PIK3CA) followed the pathways in cancer." (PMID 40179089, 2025). "RGS2 is a protein that inhibits MAPK3 and AKT signaling in zebrafish and contributes to translational arrest in dormant cancer cells." (PMID 40305273, 2025). "ERK1 and 2 though are isoforms of ERK mitogen-activated protein kinase but are coded by two different genes MAPK3 and MAPK1 respectively and show differential expressions and interdependency in different cancer cell lines." (PMID 39278984, 2024).
cancer (continued). "This correlation highlights MAPK3’s involvement in the MAPK signaling pathway, known for regulating cell proliferation and survival, especially in aggressive cancer phenotypes." (PMID 39850811, 2024). "On the contrary, signal transduction pathways associated with GPCR (R‐HSA‐388396), EGFR (R‐HSA‐177929), and MAPK1/MAPK3 signaling (R‐HSA‐5684996) were predominantly downregulated in both aging and cancer." (PMID 37888486, 2023). "Based on that AKT1, MAPK3 and ESR1 were included in cancer pathways, as well as AKT1 and MAPK3 included in the PI3K-Akt signaling pathway, the docking results again confirmed the prediction of network pharmacology." (PMID 36034875, 2022). "Some genes played well-prognostic factors in cancers, for example, MAFK in KICH, MAPK3 in PCPG and MESC, NRF2 in UVM, and PIK3CA in KIRC." (PMID 35242279, 2022). "Coincidentally, it has been reported that Oxymatrine can simultaneously inhibit both EGFR/MAPK3/1 and EGFR/CDK1 pathways to arrest the cycle in multiple cancer cell lines." (PMID 34809653, 2021). "Cytoscape analysis of gene network revealed important cancer pathways including hub genes at NFGR, MAPK3, and SMAD7 for OS, and hub genes at FOXP1, MAP2K5, FGFR1, and NOTCH2 for DFS." (PMID 31608231, 2019). "Among the KEGG-annotated pathways regulating stem cell pluripotency and pathways in cancer, several stem cell regulatory transcripts modulated by ADAR111, including AXIN2, MAPK3, and FGFR3, were enriched." (PMID 29203771, 2017). "Increased references in PubMed also provided us other hub proteins involved in cancer pathways, such as ESR1, PTEN, BCL2, AR and MAPK3." (PMID 27917343, 2016). "As one of the crucial cancer pathways, the RTK/ERK pathway is said to be one of the important links in cancer's development, containing a number of genes (EGFR, EGF, CCND1, MAPK3, etc.)." (PMID 24223781, 2013). "A number of cancer-related genes are located in these two RARs: NUPR1, MVP, MAPK3, FUS, and PYCARD are located in RAR-G12 while ERBB2, GRB7, and PPP1R1B are located in RAR-G13." (PMID 22938721, 2012). "Interestingly, central carbon metabolism in cancer (HK2, MAPK3, MYC, PFKP, PKM2, SLC16A3), galactose metabolism (B4GALT2, HK2, PFKP) and fructose and mannose metabolism (HK2, PFKFB4, PFKP) are associated with metabolism." (PMID 39924557, 2025). "The targets of some of these genes are cancer-related genes, including BDNF, NTRK2, and MAPK3." (PMID 37100464, 2023). "In conclusion, PCBs can interfere with thyroid hormone dysfunction by regulating MAPK3, MAPK1, RXRA, PIK3R1, and other potential targets, as well as the cancer pathway, PI3K-Akt signaling pathway, thyroid hormone signaling pathway, prolactin signaling pathway, and FoxO signaling pathway." (PMID 36203481, 2022). "In conclusion, the network pharmacology of this study was used to screen out the active compounds of SBG (baicalein and wogonin), 41 intersection targets (VEGFA, IL6, MAPK3, JUN, TNF, and other targets), and 20 main pathways (Pathways in cancer, IL-17, TNF signaling pathway and others)." (PMID 36415861, 2022). "Other genes related to FOXP2 that may be involved in cancer drug resistance by drug efflux according to IPA analysis of FOXP2 targets include: FOXO1, RRAS, MAPK3, PIK3R1, MRAS and PIK3CB." (PMID 29725501, 2018). "Studies indicate that MAPK3, CTTN and PXN regulate chemo or TKIs-based targeted therapy in cancer." (PMID 29556515, 2018).
cancer (continued). "The genes MAPK3, HMGB1, HMGA1, PIK3CA, and MCL1 are genes known to stimulate cellular growth; however, contrary to what is normally reported in humans, in the present study these genes were shown to be consistently expressed at lower levels in malignant tumors." (PMID 27657059, 2016). "Finally, we demonstrated that psychiatric disorders may share the same signaling pathways with cancers, involving ESR1, BCL2 and MAPK3." (PMID 27917343, 2016).
infection (297 papers, 2004 to 2026). The state of being infected such as from the introduction of a foreign agent such as serum, vaccine, antigenic substance or organism. "In particular, melatonin was shown to activate MAPK3/6 in pathogen infection and endoplasmic reticulum stress." (PMID 41226579, 2025). "Upon pathogen infection, the degree of chromatin binding of CsPRMT5 and the methylation level of MAPK3 both decreased, while the transcription level of CsMAPK3 increased." (PMID 40395926, 2025). "Collectively, these data indicate that in the incompatible interaction (G5H vs. ‘L29’), Rsv3 is induced at an early stage of infection, followed by MAPK3 activation and induction of SA genes." (PMID 37099452, 2023). "The resistant ‘L29’ cultivar responded to G5H infection by activating MAPK3 at all tested time points, while MAPK6 was only activated at 1 hpi and then declined afterward." (PMID 37099452, 2023). "The MAPK3 protein transduces signals from both PTI and ETI branches of defense signaling that leads to an output response that combats pathogen infection including parasitism by pathogenic nematodes." (PMID 35599880, 2022). "While, some of the defense-related genes that are associated with ethylene were upregulated during pathogen infection of RF (BSMT1, MLO6, MAPK3, PR1, PDR1, PER15, TLP, UBA2a, UGT74E2)." (PMID 33423039, 2021). "Meanwhile, mitogen-activated protein kinase 3 (Mapk3) and serum response factor (Srf) were persistently downregulated throughout infection." (PMID 22679491, 2012). "Notably, under pathogen infection conditions, the reduced binding ability of CsPRMT5 to chromatin leads to a decrease in H4R3sme2 levels, which subsequently activates the transcription of immune-regulatory genes such as MAPK3." (PMID 40395926, 2025). "Infection by pathogenic bacteria may also cause increased levels of H2O2 and NO, leading to enhanced endogenous melatonin level activation of the MAPK cascade via OXI1/MAPKKK3, MAPKK4/5/7/9 and MAPK3/6." (PMID 39126104, 2024). "The mRNA levels of Mapk3 (Erk1) and Mapk10 (Jnk3) decrease upon FM1 infection but increase with XDY treatment." (PMID 39897040, 2025). "NO and H2O2 levels rise during infection, leading to higher endogenous melatonin levels and activation of the MAPK cascade via OXI1/MAPKKK3, MAPKK4/5/7/9, and MAPK3/6." (PMID 39126104, 2024). "Urinary MAPK-3 was more expressed in patients with chronic bilharzial infection, and in those with high IHA titer compared to those with recent infection and low antibody titer respectively, showing a highly significant difference (p value = 0.001)." (PMID 33139749, 2020). "We noted that Mapk3 (Erk1) mRNA and Mapk10 (Jnk3) mRNA were reduced during FM1 infection, but enhanced with XDY treatment." (PMID 32957919, 2020). "The integrin signaling mediators BCAR1 and NEDD9, as well as MAPK3 and the SRC homology domain-containing protein SHC1, showed a strong, time-dependent phosphorylation after 90 min of infection, returning to control levels by 7 h post-infection." (PMID 25101063, 2014). "In line with previous observations, the expression of kinases belonging to the ERK signaling cascade (MAPK1, MAPK3, MAP2K1, and MAP2K2) remained unaltered after infection, while the levels of some proteins involved in MAPK14/p38 signaling changed significantly." (PMID 36298696, 2022). "Likewise, the Trefoil Factor Initiated Mucosal Healing pathways were significantly suppressed in early stage of infection, more specifically, PTK2, GHR, RHOA, CTNNB1, MAPK3, and SHC1 genes." (PMID 24349118, 2013). "The infection also modifies the expression of MAPK cascade in HCN-2, but in our MSCs, MAPK1 and MAPK3 levels were decreased, and JNK, p38, and ISG15 did not change their values." (PMID 34769246, 2021).
neurological diseases (21 papers, 2015 to 2025). "Some genes, such as CD2AP, FCER1G, MAPK3, and EPHX2, were in nodes or core nodes of this neurological disease network, indicating that the CpG sites and these target genes may influence AD development." (PMID 38092781, 2023).
neurodevelopmental disorder (7 papers, 2022 to 2024). A behavioral and cognitive disorder with onset during the developmental period that involves impaired or aberrant development of intellectual, motor, or social functions. "The MAPK3 gene (encoding ERK1) and the major vault protein gene (MVP), both involved in the ERK/MAP kinase pathway, are associated with neurodevelopmental disorders." (PMID 38203422, 2023). "Consistent with this, chromosomal duplications or deletions of 16p11.2, which includes the MAPK3 gene encoding for ERK1, or a microdeletion on chromosome 22, which contains the MAPK1 gene coding for ERK2, are commonly found to be associated with neurodevelopmental disorders and ASD." (PMID 35626639, 2022).
retinal disorder (1 paper, 2025). Any disease or disorder of the retina. "EGFR inhibition has been linked to reduced fibrotic remodeling in retinal disorders, while MAPK3 signaling plays a context-dependent role in cell survival and differentiation." (PMID 40508210, 2025).
MAPK3 also shares sentences with these, for which no sentence is quoted: glioblastoma (173 papers); neuroblastoma (97); osteosarcoma (88); leukemia (75); Hyperglycemia (72); endometrial cancer (55); oral cancer (54); pulmonary fibrosis (49); multiple myeloma (44); colitis (42); renal fibrosis (41); thyroid cancer (41); triple-negative breast carcinoma (36); breast tumors (35); lymphoma (32); nasopharyngeal carcinoma (28); cardiovascular disease (27); Myocardial fibrosis (27); neurodegenerative disease (26); renal cell carcinoma (26); endometriosis (24); injury (24); squamous cell carcinoma (23); esophageal cancer (21); Arthritis (19); cholangiocarcinoma (19); diabetic nephropathy (19); Dyskinesia (18); fibrosis (18); hypertrophy (18).
A further 651 diseases each share a sentence with MAPK3 in 18 papers or fewer.